FOXP3 (forkhead box P3)
Diseases named in the same sentence as FOXP3 in open-access papers (continued):
Sharing a sentence is not in itself a finding about the gene and the disease.
colorectal cancer (continued). "We show an association between HMGB1 expression intensity and density of immune cell subsets in colorectal cancer; nuclear and cytoplasmic HMBG1 associated with increased CD4+ lymphocytes, and nuclear HMGB1 associated with increased FOXP3+ and ICOS+ lymphocytes and reduced CD8+ T-cells." (PMID 36980751, 2023). "The prognosis of colorectal cancer patients with increased numbers of Tregs has also been controversial, which may be attributed to an improper interpretation of heterogeneous FOXP3+ cells as a single population of Tregs." (PMID 35402515, 2022). "For instance, hypoxia induced the expression of IL-17 in FOXP3+ Tregs in colorectal cáncer (CRC), FOXP3+IL-17+ T cells were then capable of inducing CRC-associated cell markers in bone marrow-derived mononuclear cells and drove the cells to be cancer-initiating cells." (PMID 34026764, 2021). "Therefore, we herein studied the prognostic significance of the presence and location of CD3+, CD8+, and FoxP3+ T lymphocytes in colorectal cancer samples." (PMID 34440038, 2021). "However, in some cancers, including colorectal cancer, a high number of tumor‐infiltrating CD4+FOXP3+ T cells was shown to be associated with improved survival." (PMID 32377339, 2020). "Furthermore, in colorectal cancer patients, IL-35 expression was correlated with the severity of malignancy, cancer clinical stage, and the number of peripheral Foxp3+-Tregs33." (PMID 32973297, 2020). "Recent studies have explored the potential prognostic value of a set of colorectal cancer stem cell markers—CD133, LGR5, ALDH1, CD44v6 and SOX2—investigated alone or in association with immune-related cell markers—CD3, CD8, Foxp3 and PD-L1—in 104 stage III colorectal cancer patients." (PMID 29652830, 2018). "Recent data demonstrating that both strongly immunosuppressive Foxp3hi and weakly immunosuppressive Foxp3lo Treg TILs detected in colorectal cancer patients produce IL-17 further validate the relevance of such de novo Foxp3 expression in human IL17-producing T cells." (PMID 28290453, 2017). "We expect the development of activators targeting FOXP3 for colorectal cancer treatment." (PMID 28591725, 2017). "Indeed, a recent study has suggested that colorectal cancer tissue-derived Foxp3+ IL-17+ cells have the capacity to induce cancer-initiating cells in vitro." (PMID 28160571, 2017). "However, the prognostic implication of tumor-infiltrating FoxP3+ Tregs in patients with colorectal cancer (CRC) still remains controversial." (PMID 29209232, 2017). "The expression of TSDR-DMR and FOXP3 mRNA was investigated in various colorectal cancer cell lines." (PMID 24938080, 2014). "Besides its expression in T-regs and transiently in activated CD4+ T helper cells, the forkhead transcription factor 3 (FoxP3) has been also detected in various tumor cells, e.g. colorectal cancer and PDAC." (PMID 24797069, 2014). "Given that GALT environment is permissive for induction of iTreg cells, it is tempting to speculate that the FOXP3+ Treg cells in colorectal cancer are mostly iTreg cells." (PMID 23874336, 2013). "However, in colorectal cancers FOXP3+ T-cell infiltration has been found to correlate with significantly improved prognosis by us and others." (PMID 22471961, 2012). "Studies in murine models with Usp22 deletion showed a decreased FoxP3 stability, reducing the immunosuppressive activity of Tregs and promoting a stronger antitumor response, suggesting its potential as a therapeutic target in cancers such as melanoma and colorectal cancer." (PMID 41394821, 2025). "Interestingly, analysis of the independent human colorectal cancer cohort from TCGA (The Cancer Genome Atlas) database demonstrated that patients with higher level of Bcl6 (in Foxp3+CD4+ cells) showed significantly poorer overall survival compared to those with a lower level." (PMID 32477338, 2020). "However, FOXP3+ T cells predict a favorable prognosis of colorectal cancer." (PMID 31118034, 2019).
colorectal cancer (continued). "However, the role of FoxP3+ Tregs in human colorectal cancer (CRC) remains controversial." (PMID 29088871, 2017). "It was expected that the regulatory T cell infiltration into the tumour would be negatively associated with patient outcome; however, regulatory (FoxP3+) T cells have been shown to have a protective role in colorectal cancer, in contrast to their negative role in many other cancers." (PMID 21864372, 2011). "In colorectal cancer, liver metastasis, CD4+FOXP3+ Tregs, and increased levels of α-smooth muscle actin, HGF, and c-MET indicate potential therapeutic targets for this metastatic form of colorectal cancer." (PMID 40281554, 2025). "For instance, in colorectal cancer, a higher CD8+/FOXP3+ ratio was an independent predictor of improved overall survival when assessed by immunohistochemistry." (PMID 41394821, 2025). "Here, we revealed that a high level of TNF-α in the colorectal cancer (CRC) microenvironment upregulated CCR8 expression in Tregs via the TNFR2/NF-κB signalling pathway and the FOXP3 transcription factor." (PMID 37935468, 2024). "In colorectal cancer liver metastasis, the emergence of CD4+FOXP3+ Tregs, coupled with elevated levels of α-smooth muscle Actin, HGF, and c-MET, suggests potential therapeutic targets for this metastatic variant of colorectal cancer." (PMID 39664377, 2024). "In colorectal cancer, an inverse relationship was found between the systemic inflammatory response (elevated CRP with cut-off 10 mg/L) and FoxP3+ Tregs infiltration in the intratumor stroma." (PMID 36980787, 2023). "We analysed 12,592 tissue microarray (TMA) spots from 3,545 colorectal cancers sourced from more than 240 institutions in two clinical trials (QUASAR 2 and SCOT) stained for CD4, CD8, CD20, CD68, FoxP3, pan‐cytokeratin, and DAPI by mIF." (PMID 37697694, 2023). "We analyzed the immune cell infiltrates of head and neck squamous cell carcinoma and colorectal cancers and identified a subset of CD4+ Th cells distinct from FOXP3+ Tregs that coexpressed programmed cell death 1 (PD-1) and ICOS." (PMID 35439168, 2022). "In other types of cancers, like colorectal cancer, CD4+CD25+FOXP3+ Tregs are extensively increased in tumors in correlation with their stages." (PMID 34055618, 2021). "In colorectal cancer patients, studies have successfully isolated CD8+CD25+FoxP3+ Treg lymphocytes directly from a tumor." (PMID 30155493, 2018). "However, several studies reported a favorable role of FOXP3+ T-cells in colorectal carcinomas (CRC)." (PMID 29887862, 2018). "Some authors reported good prognostic value of Foxp3+CD4+ T cells in head and neck cancer, colorectal carcinoma bladder cancer and lymphoma." (PMID 26604855, 2015). "Studies found that in prostate cancer and colorectal cancer patients, the numbers CD8+CD25+Foxp3+ T cells in the peripheral blood of patients and the local regions of cancer increased." (PMID 23587428, 2013). "In this study we examined the lymph nodes of Stage II colorectal cancer patients to identify CD4+, CD8+ and Foxp3+ cell populations and correlated these with patient outcome, alone, and in combination with other clinico-pathological variables." (PMID 21864372, 2011). "Using an antibody directed against the regulatory T-cell marker transcription factor forkhead box P3 (FOXP3), regulatory T cells were examined in 70 colorectal cancers with known MSI status (MSI-H, n=37; microsatellite stable, n=33)." (PMID 18985040, 2008). "Interestingly, in a MSI-high colorectal cancer xenograft mouse model, infection with Lactobacillus synergized with anti-PD1 therapy by enhancing CD8+ T cells and reducing Foxp3+CD25+ Treg intratumoural cell infiltration." (PMID 40113862, 2025). "LAP+ T cells, which include some Foxp3+ T cells, increase in patients with colorectal cancer, non-muscle-invasive and muscle-invasive urinary bladder cancer, and other cancers." (PMID 40053558, 2025).
colorectal cancer (continued). "Subsequent studies into Tregs in these unique cases indicated that the predominant phenotype of FOXP3+ CD4+ T cells among such colorectal cancers was CD45RA-CD25LOWFOXP3LOW, labeled as non-Tregs." (PMID 38500876, 2024). "Furthermore, a functionally distinct subpopulation of tumor-infiltrating Foxp3+ T cells, secreting interleukin (IL)-12 and transforming growth factor (TGF)-β, showed significantly favorable prognosis in colorectal cancers." (PMID 38023184, 2023). "We recently reported the relapse-free survival (RFS) significance of the combination of CD4+ and forkhead box P3+ (FOXP3) T-cell densities identified by immunohistochemistry in patients with stage I, II, and III colorectal cancer (CRC) who underwent curative resections." (PMID 36253752, 2022). "Foxp3+ regulatory T cells in draining lymph nodes contribute to tumor development and may lead to CD8+ T-cell incompetence in colorectal cancer." (PMID 35749551, 2022). "A high concentration of IL-24 could also downregulate the Treg percentage (i.e., FoxP3 mRNA) and promote CD4+ T cell proliferation in colorectal cancer." (PMID 35752792, 2022). "Tumour-infiltrating FoxP3+ regulatory T cells have been identified as both positive and negative prognostic factors in colorectal cancer (CRC) and rectal cancer (RC)." (PMID 35140715, 2022). "Furthermore, CD4+ T cells that highly expressed the forkhead box P3 (FOXP3) suppressed the anti‐tumor immunity and suggested a poorer prognosis in colorectal cancers." (PMID 34668652, 2021). "Using mass cytometry and single-cell mRNA sequencing, we identify a tumor-infiltrating MAIT cell subset expressing CD4 and Foxp3 and observe high expression of CD39 on MAIT cells from colorectal cancer (CRC) only, which we show in vitro to be expressed specifically after TCR stimulation." (PMID 33205061, 2020). "In addition, Tregs can also be divided into different subtypes according to the expression levels of Foxp3 and CD45RA, and the prognosis of patients with colorectal cancer is closely related to the infiltrating Treg subtype." (PMID 30477520, 2018). "In colorectal cancer tissue, tumour CD247 (PD-L1) is inversely associated with FoxP3+, but not CD3+, CD8+ or CD45RO+ cell density." (PMID 29245908, 2017). "In agreement, in the setting of colorectal cancer, CD8+FOXP3+CD25+ T-cells were significantly increased in peripheral blood and in colorectal cancer tissue, indicating that these cells may contribute to tumor immune escape and disease progression." (PMID 26284077, 2015). "A study investigating the impact of 5-FU chemotherapy on gut inflammation showed that in AOM/DSS-induced colorectal cancer model mouse treated with 5FU, significantly elevated expression of intestinal inflammatory genes was found, including TNF-α, MCP-1, NOS2, IL6, IL1-β, and FOXP3." (PMID 34337082, 2021). "However, for some types of tumors, such as esophageal cancer and colorectal cancer (CRC), a large number of FOXP3 + Tregs in tumors may be a marker of good prognosis." (PMID 33466316, 2021). "FOXP3 expression and TSDR demethylation have been widely used as prognostic markers for determining the proportion of Treg cells in peripheral blood from healthy individuals and in certain diseases such as ovary, breast and colorectal cancers and other solid tumors." (PMID 30455694, 2018). "For colorectal cancer (CRC) the clinical relevance of Foxp3 has not been evaluated in detail." (PMID 23382847, 2013). "Here, we present clear evidence that FOXP3+ T cells derived from patients with CLL, MGUS, MM, follicular lymphoma (FL), Hodgkin's disease (HD), and colorectal cancer (CRC) are lacking CD127." (PMID 21904560, 2011).
gastric cancer (153 papers, 2008 to 2026). A primary or metastatic malignant neoplasm involving the stomach. "TCGA gastric cancer data confirmed a positive correlation between Foxp3 and IL-10, TGF-β1 expression, and linked these molecules to poor prognosis in gastric cancer patients." (PMID 41438510, 2025). "Tumor-infiltrating CD8+ T cells and CD68+ TAMs in resected gastric cancer are predictive of the postoperative prognosis and benefits of adjuvant chemotherapy, whereas FOXP3+ T-cell infiltration is associated with worse outcomes." (PMID 39679910, 2025). "An in-depth study of the role and underlying mechanism of FOXP3 in gastric cancer cells is of great importance." (PMID 39315286, 2024). "On the other hand, low expression of TLS and FOXP3 was significantly associated in gastric cancer and liver cancer patients." (PMID 39259184, 2024). "Previous studies have shown a positive association between nuclear FOXP3 expression in tumor cells and survival in breast cancer, gastric cancer, and hepatocellular carcinoma." (PMID 39672307, 2024). "A retrospective analysis in gastric cancer reveals that high Foxp3+ Treg infiltration in stages I–II is associated with higher five-year survival rates, contrasting with poorer outcomes in stages III–IV." (PMID 39000453, 2024). "Nevertheless, the expression of FoxP3 was found to be associated with the degree of gastric cancer differentiation, and it can promote gastric cancer proliferation, migration, and invasion through the TGF-β pathway." (PMID 37569676, 2023). "More importantly, the activity of FOXP3 has been shown to be associated with gastric cancer cell invasion and proliferation." (PMID 35037550, 2022). "Tumor-infiltrating FoxP3+ Tregs were associated with better survival in colorectal, head and neck, and esophageal cancers, and higher tumor-infiltrating Foxp3+ cells were associated with better OS in patients with resected gastric cancer." (PMID 34086741, 2021). "In this setting increased CD4+FoxP3+ expressing T cells following PD-1 inhibition are associated with hyperprogression in patients with gastric cancer." (PMID 32183719, 2020). "In a recent meta-analysis, FOXP3+ Treg infiltration was found to be associated with poor prognosis in hepatocellular cancer and gastric cancer patients and good prognosis in CRC patients." (PMID 33062072, 2020). "In gastric cancer, evidence are found that higher Foxp3+ Tregs in blood and GC tissue are associated with the shorter OS 13-14,16." (PMID 31777600, 2019). "Particularly, decreased NOVA1 in T cells within the gastric cancer tissues was correlated with decreased FOXP3-positive regulatory T cells and was associated with poor patient prognosis." (PMID 26673617, 2016). "Many studies have reported the association between HLA-G-positive gastric cancer patient and poor survival, with a recent study suggesting the tumor escape mechanism by increasing Foxp3 + Treg lymphocytes and decreasing CD8 + T lymphocytes in GC." (PMID 26627200, 2015). "Base on those studies, our meta-analysis suggested a high density of FoxP3+ Tregs was associated with poor survival and high recurrences for gastric cancer." (PMID 26462617, 2015). "The association between the expression level of FOXP3 and clinical characteristics of the 133 patients with gastric cancer was also included in the present study." (PMID 24040244, 2013). "Extensive Foxp3+ Treg infiltration and a high Foxp3+/CD8+ ratio are also associated with poor prognosis in gastric cancer." (PMID 22526791, 2012). "Thus, Medical professionals have shown that Foxp3+Treg expression is elevated in high-grade digestive malignant tumors, such as liver, pancreatic, and stomach cancers, and is typically linked to a poor prognosis for patients." (PMID 38919615, 2024). "Furthermore, it has been reported that Foxp3+ Tregs are highly expressed in gastric cancer and are associated with poor clinical outcomes." (PMID 38561388, 2024).
gastric cancer (continued). "Furthermore, integrating CD8+T:Foxp3 ratios, which increased the complexity for immune phenotype status, revealed 6–7 clusters that enabled the separation of gastric cancer patients at the same clinical stage into different risk-group subsets." (PMID 29025424, 2017). "However, contrasting findings have also been shown where infiltration of FoxP3+ TILs was found to be associated with poor prognosis in gastric cancer patients." (PMID 29069772, 2017). "In this study, we explored whether CCR7 expression in gastric cancer cells and intratumoral FOXP3+ Tregs were associated with clinicopathological factors and could be used as a prognostic indicator." (PMID 24040244, 2013). "It is well known that CD8+ T cells in gastric cancer tissues are favorable for prognosis of GC patients and Foxp3+ Tregs are negatively associated with survival of GC patients." (PMID 33093811, 2020). "In conclusion, our results demonstrated that both high CCR7 expression in tumor cells and increased intratumoral FOXP3+ Tregs were associated with worse OS in gastric cancer, positively correlated with each other, and could be considered as a co-indicator of clinical prognosis of gastric cancer." (PMID 24040244, 2013). "Gaiella has been detected in the gastric mucosa of patients with gastric cancer, where its abundance was negatively correlated with Foxp3+ regulatory T cells, suggesting immunostimulatory properties." (PMID 40489758, 2025). "In gastric cancer, Foxp3, IL-10, and TGF-β1 create a tightly coordinated immunosuppressive synergistic network." (PMID 41438510, 2025). "We examined continuous tissue sections from 80 gastric cancer patients using dual staining for CCR8/Foxp3 and GzmB/CD8." (PMID 41323783, 2025). "FOXP3 is significantly overexpressed in gastric cancer tissues compared with adjacent normal mucosa." (PMID 41229433, 2025). "Foxp3, IL-10, and TGF-β1 exhibit significant co-expression in gastric cancer and are strongly associated with the presence of tumor-infiltrating immune cells." (PMID 41438510, 2025). "An enrichment of IL10+ CD19+CD24hiCD38hi Bregs promoting the conversion of effector T cells into Foxp3+ Tregs in vitro was identified in breast and gastric cancer patients." (PMID 39346706, 2024). "Regulatory T (Treg) cells expressing the Foxp3 transcription factor play a critical role in promoting the stemness of gastric cancer cells through the IL13/STAT3 pathway and also help in reducing overactive immune responses within the tumor microenvironment." (PMID 39605357, 2024). "The expression levels of IL-6, IL-17, FoxP3, and TGF-β1 in cancerous tissues were significantly higher than those in the control group and were associated with clinical staging of gastric cancer." (PMID 39676857, 2024). "The literature has indicated that FoxP3 is a tumor suppressor in breast, prostate, and gastric cancers." (PMID 37569676, 2023). "Comparable results were shown in gastric cancer, where co-expression of FOXP3 and CMTM6 was related to a favorable prognosis." (PMID 38067301, 2023). "We performed Kaplan‒Meier survival analysis in our investigation of the combined effects of CLDN18.2 with tumour-infiltrating lymphocytes (TILs), PD-L1, HER2, or Foxp3 on the prognosis of gastric cancer (GC)." (PMID 37582713, 2023). "The results demonstrated that the knockdown of DNAAF3 led to a decrease in the expression of β-Catenin and its downstream target CCL28 in gastric cancer, resulting in the suppression of Treg cell (FOXP3+) infiltration." (PMID 37711621, 2023). "Gastric cancers have shown adverse outcomes with high tumor FOXP3+ Tregs, similar to the finding in this study." (PMID 36368129, 2023). "This is in accordance with a previous study in gastric cancer, where CD47 expression was linked with a lower CD8/FOXP3 ratio." (PMID 35406573, 2022). "FOXP3 promotes the proliferation and inhibits apoptosis in gastric cancer cells by binding to the PSMD7 promoter." (PMID 35037550, 2022).